HMGB2 (high mobility group box 2)
Description:
Multifunctional protein with various roles in different cellular compartments. May act in a redox sensitive manner. In the nucleus is an abundant chromatin-associated non-histone protein involved in transcription, chromatin remodeling and V(D)J recombination and probably other processes. Binds DNA with a preference to non-canonical DNA structures such as single-stranded DNA. Can bent DNA and enhance DNA flexibility by looping thus providing a mechanism to promote activities on various gene promoters by enhancing transcription factor binding and/or bringing distant regulatory sequences into close proximity. Involved in V(D)J recombination by acting as a cofactor of the RAG complex: acts by stimulating cleavage and RAG protein binding at the 23 bp spacer of conserved recombination signal sequences (RSS) (By similarity). Proposed to be involved in the innate immune response to nucleic acids by acting as a promiscuous immunogenic DNA/RNA sensor which cooperates with subsequent discriminative sensing by specific pattern recognition receptors (By similarity). In the extracellular compartment acts as a chemokine. Promotes proliferation and migration of endothelial cells implicating AGER/RAGE. Has antimicrobial activity in gastrointestinal epithelial tissues. Involved in inflammatory response to antigenic stimulus coupled with pro-inflammatory activity (By similarity). Involved in modulation of neurogenesis probably by regulation of neural stem proliferation (By similarity). Involved in articular cartilage surface maintenance implicating LEF1 and the Wnt/beta-catenin pathway (By similarity).
Synonyms: HMG2
Tractability: Antibody: UniProt places it where antibodies can reach, with high confidence; its Gene Ontology location is reachable by antibodies, with medium confidence. PROTAC: ubiquitination databases record sites on it; its protein half-life has been measured.
Gene: Protein-coding gene on chromosome 4 (173,331,376 to 173,334,456, reverse strand). Ensembl gene ENSG00000164104.
Subcellular location: Nucleus; Chromosome; Cytoplasm; Secreted
Subcellular location (Human Protein Atlas): Nucleoplasm; Annulus; Nucleoli; Principal piece; Predicted to be secreted
Pathways (Reactome):
Programmed Cell Death: Apoptosis induced DNA fragmentation
Gene Ontology:
Molecular function: chemoattractant activity; damaged DNA binding; DNA binding; DNA binding, bending; protein binding; RAGE receptor binding; RNA binding; transcription cis-regulatory region binding; transcription coactivator activity; cis-regulatory region sequence-specific DNA binding; double-stranded DNA binding; four-way junction DNA binding; non-sequence-specific DNA binding, bending; single-stranded DNA binding; supercoiled DNA binding; DNA-binding transcription factor binding; protein domain specific binding
Biological process: cell chemotaxis; cellular response to lipopolysaccharide; defense response to Gram-negative bacterium; defense response to Gram-positive bacterium; negative regulation of DNA-templated transcription; negative regulation of transcription by RNA polymerase II; positive regulation of DNA-templated transcription; positive regulation of endothelial cell proliferation; positive regulation of erythrocyte differentiation; positive regulation of megakaryocyte differentiation; positive regulation of transcription by RNA polymerase II; regulation of transcription by RNA polymerase II; base-excision repair; chromatin organization; chromatin remodeling; DNA geometric change; DNA topological change; double-strand break repair via nonhomologous end joining; granzyme-mediated apoptotic signaling pathway; inflammatory response to antigenic stimulus; nucleosome assembly; regulation of neurogenesis; regulation of stem cell proliferation; response to lipopolysaccharide; V(D)J recombination; and 6 more
Cellular component: chromosome; condensed chromosome; cytoplasm; extracellular region; nucleolus; nucleoplasm; nucleus; perinuclear region of cytoplasm; protein-containing complex; chromatin; endoplasmic reticulum
Genetic constraint (gnomAD): Loss-of-function variants: 2 observed, 22.17 expected, observed/expected ratio (o/e) 0.0902, 90% interval 0.036 to 0.28. The upper end of that interval is the gene's LOEUF score, 0.28, which puts it in group 1 of 6, group 1 being the genes least tolerant of losing a copy. Missense variants: 159 observed, 253.95 expected, observed/expected ratio (o/e) 0.63, 90% interval 0.55 to 0.71. Synonymous variants: 92 observed, 88.87 expected, observed/expected ratio (o/e) 1.04, 90% interval 0.87 to 1.23.
Homologues: Orthologues: chimpanzee HMGB2 (100% identical), macaque HMGB2 (100% identical), dog HMGB2 (99% identical), pig HMGB2 (99% identical), rat Hmgb2 (99% identical), rat Hmgb2l1 (99% identical), guinea pig HMGB2 (98% identical), mouse Hmgb2 (97% identical), rat Hmgb2l2 (97% identical), tropical clawed frog hmgb2 (84% identical), zebrafish hmgb2a (75% identical), Caenorhabditis elegans hmg-4 (23% identical), and 1 more. Paralogues in human: HMGB1 (79% identical), HMGB1P1 (75% identical), HMGB3 (70% identical), HMGB4 (38% identical), UBTF (31% identical), SSRP1 (29% identical), TOX2 (28% identical), TOX3 (27% identical), TOX4 (26% identical), TOX (24% identical), SP100 (22% identical), HMGXB4 (22% identical), and 8 more.
Diseases named in the same sentence as HMGB2 in open-access papers:
HMGB2 is named in the same sentence as 114 diseases in open-access papers, as found by Europe PMC text mining. Sharing a sentence is not in itself a finding about the gene and the disease. The quoted sentences say what the papers report.
breast carcinoma (18 papers, 2013 to 2025). "There is astudy suggested that HMGB2 is associated with malignancy and regulates Warburgeffect in human breast cancer by targeting lactate dehydrogenase B andfructose-bisphosphatase 1.HMGB2 is expressed in patients with OC and associated with prognosis and tumormetastasis." (PMID 35129574, 2022). "Additionally, high expression of HMGB2 was associated with a poor prognosis for the patients with breast cancer via promoting cell proliferation and glycolysis in breast cancer cells." (PMID 33407071, 2021). "The impact of HMGB2 knockdown on the migration abilities of eight cancer cell lines representing breast cancer, cervical cancer, ovarian cancer, and endometrial cancer was analyzed using the Transwell migration assay." (PMID 40396172, 2025). "In breast cancer cells, HMGB2 knockdown markedly reduced proliferation in both MDA-MB-231 and T47D cell lines." (PMID 40396172, 2025). "The impact of HMGB2 knockdown on the invasive abilities of eight cancer cell lines representing breast cancer, cervical cancer, ovarian cancer, and endometrial cancer was analyzed using the Transwell invasion assay." (PMID 40396172, 2025). "Further research is necessary to determine how imperatorin reduce the expression of HMGB2 in breast cancer cells." (PMID 36627680, 2023). "HMGB2 promotes the progression of breast cancer by targeting lactate dehydrogenase B and febrile convulsions 1 proteins." (PMID 35962344, 2022). "In breast cancer, the HMGB2 is regulated with ER, LDHB, and FBP1 to promote the endocrine therapy resistance and tumorigenesis of tumor cells." (PMID 35962344, 2022). "For instance, the expression of IRF2 has been found to be related to breast cancer, and it has been reported that HMGB2 directly and significantly promotes breast cancer progression." (PMID 33537063, 2020). "HMGB2 expression plays important roles in breast cancer progression by regulating proliferation and the Warburg effect by transcriptional regulation of LDHB and FBP1 activity." (PMID 29463261, 2018). "The frequent upregulation of HMGB2 expression in human breast cancer cells highlights its potential as a novel therapeutic target for this cancer." (PMID 29463261, 2018). "The present study investigated the clinicopathologic significance of HMGB2 expression in a large number of breast cancer cases via an immunohistochemistry study." (PMID 29463261, 2018). "Experimentally, knockdown of HMGB2 expression by stable transfected shRNA significantly decreased the growth and glycolysis of breast cancer cells both in vitro and in mouse models." (PMID 29463261, 2018). "To determine the effect of altered HMGB2 expression on aerobic glycolysis in breast cancer cells, we calculated the glucose utilization and lactate concentrations of the HMGB2 stable knockdown cells." (PMID 29463261, 2018). "Our study demonstrates that high HMGB2 predicts a poor prognosis by promoting cell proliferation and glycolysis in breast cancer cells." (PMID 29463261, 2018). "Recent study indicated that HMGB2 was a positive regulator of proliferation and glycolysis in breast cancer cells." (PMID 30301189, 2018). "A Cox proportional hazards model revealed that HMGB2 expression was an independent prognostic factor for breast cancer after radical resection (P < 0.05)." (PMID 29463261, 2018). "Mechanically, promotion of breast cancer progression by HMGB2 directly and significantly correlated with activation of LDHB expression and inactivation of FBP1 expression." (PMID 29463261, 2018). "HMGB2 was more highly expressed in tumor-cell nuclei of breast cancer cells than in the adjacent normal breast tissues (P < 0.05)." (PMID 29463261, 2018). "In the present study, we focused on the important oncogene HMGB2 and revealed for the first time the functional role of HMGB2 in regulating cell proliferation and the Warburg effect in breast cancer tissues." (PMID 29463261, 2018).
breast carcinoma (continued). "Taken together, these results validated HMGB2 as a positive regulator of cell proliferation in breast cancer tissues." (PMID 29463261, 2018). "In terms of prognosis of breast cancer, high expression of HMGB2 and PDGFRA in breast cancer indicated poor prognosis, while high expression of HSD17B in breast cancer suggested the opposite effect." (PMID 29050221, 2017). "Overexpression of HMGB1 and HMGB2 has been observed in several human cancer types, including hepatocellular, skin squamous cell, prostate, gastrointestinal and breast carcinomas." (PMID 23426143, 2013). "HMGB2 expression was identified in the nucleus of breast cancer cells." (PMID 29463261, 2018). "We have defined in this study a novel function of HMGB2 in breast cancer." (PMID 29463261, 2018). "The result indicates that HMGB2 may affect the initiation, progression, and metastasis of breast cancer." (PMID 29463261, 2018). "Our data implies that HMGB2 may serve as a potential prognostic marker in breast cancer clinical practice." (PMID 29463261, 2018). "In addition, HMGB2 has been demonstrated to be significantly downregulated by the anti-human epidermal growth factor receptor 2 antibody through the AKT pathway in breast cancer cell lines." (PMID 23426143, 2013). "However, little is known about HMGB2 expression and its prognostic significance in breast cancer." (PMID 29463261, 2018). "Furthermore, HMGB2 was a positive regulator of proliferation and glycolysis in breast cancer cells." (PMID 29463261, 2018). "However, the clinical significance of HMGB2 signaling in human breast cancer progression remains unknown." (PMID 29463261, 2018). "HMGB2 promotes LDHB expression and inhibits FBP1 expression, which in turn promotes breast cancer growth via boosting the Warburg effect." (PMID 40100307, 2025). "In breast cancer cell lines, MDA-MB-231 and T47D, HMGB2 knockdown significantly decreased the proportion of EdU-positive cells after Palbociclib treatment." (PMID 40396172, 2025). "In breast cancer cell lines (MDA-MB-231 and T47D), HMGB2 knockdown significantly inhibited cell invasion." (PMID 40396172, 2025). "In breast cancer cell lines (MDA-MB-231 and T47D), HMGB2 knockdown significantly inhibited cell migration." (PMID 40396172, 2025). "In vitro assays revealed a significant decrease in tumor cell proliferation across multiple cancer cell lines, including MDA-MB-231 (breast cancer), HeLa (cervical cancer), SKOV3 (ovarian cancer), and Ishikawa (endometrial cancer), following HMGB2 knockdown and Palbociclib treatment." (PMID 40396172, 2025). "Our analysis revealed that the five unique hub genes (PPARG, HIPK2, ZFP36L1, HMGB2 and ALDH1A3) may constitute a gene expression signature specifying a therapeutic response of ERβ1-expressing ERα-positive breast cancer cells to treatment with OHT+ATRA." (PMID 36835157, 2023). "To confirm the oncogene role of HMGB2 in cancer cell growth and the Warburg effect in vivo, we performed tumorigenesis assays in nude mice by subcutaneous injection of MCF-7-scramble/MCF-7-shHMGB2 breast cancer cells." (PMID 29463261, 2018). "Interestingly, the MDA-MB-231-LM3 breast cancer TuNEPs exhibited a group of RAGE agonists, including HMGB1 and HMGB2, which were absent in PC9 lung cancer TuNEPs." (PMID 40751052, 2025).
gastric cancer (14 papers, 2015 to 2025). A primary or metastatic malignant neoplasm involving the stomach. "Hmgb1/2 inhibits genotoxic stress in polyglutamine diseases by interacting with mutant ataxin-1 and huntingtin protein; suppressing Hmgb2 expression causes gastric cancer cells to be less sensitive to chemotherapy." (PMID 35574435, 2022). "In gastric cancer, the high expression of HMGB2 predicts a poor prognosis and its expression is regulated by non-coding RNA, miRNA-23b-3p, miRNA-1297, MALAT1, and miRNA-873 to promote the proliferation, migration, and invasion of cells." (PMID 35962344, 2022). "In gastric cancer, HMGB2 indicates a poor prognosis and is involved in tumor progression along with microRNAs, long non-coding RNAs, and proteins." (PMID 35962344, 2022). "In summary, CENPU was an upstream protein of HMGB2, which regulated proliferation and glycolysis of gastric cancer." (PMID 34872447, 2021). "In this work, we aimed to investigate the regulatory role of CENPU in gastric cancer and its correlation with HMGB2, and their effects on glycolytic metabolism." (PMID 34872447, 2021). "Knockdown of HMGB2 significantly suppressed proliferation, invasion, and glycolysis of gastric cancer cells." (PMID 34872447, 2021). "This study demonstrated that downregulation of CENPU inhibited cell proliferation and glycolysis of gastric cancer by regulating HMGB2." (PMID 34872447, 2021). "In the present study, we demonstrated that CENPU promoted proliferation and glycolysis of gastric cancer cells via HMGB2." (PMID 34872447, 2021). "In this work, we identified that CENPU is upstream of HMGB2, which regulated proliferation and glycolysis of gastric cancer." (PMID 34872447, 2021). "Taken together, CENPU is an upstream factor of HMGB2, which regulates proliferation and glycolysis of gastric cancer." (PMID 34872447, 2021). "Next the effect of CENPU on the expression level of HMGB2 and their roles in proliferation and glycolysis in gastric cancer cells were investigated." (PMID 34872447, 2021). "Similar to our predictive analysis, HMGB2 was found to promote gastric cancer cell autophagy and induce multidrug resistance by directly interacting with miR-23b-3p." (PMID 31695969, 2019). "Overexpression of HMGB2 may promote chemoresistance in gastric cancer cells by suppressing miR‐23b‐3p function." (PMID 41354099, 2025). "In gastric cancer, overexpression of HMGB2 drives glycolysis through two main signaling pathways." (PMID 41220952, 2025). "Furthermore, HMGB2 overexpression contributes to chemoresistance in gastric cancer by enhancing energy production through glycolysis, enabling cells to survive chemotherapy or radiation stress." (PMID 41220952, 2025). "Knockdown of HMGB2 inhibits proliferation and glycolysis in gastric cancer cells." (PMID 34872447, 2021). "High mobility group box 2 (HMGB2) is identified as a biomarker to diagnose of gastric cancer." (PMID 34872447, 2021). "Knockdown of HMGB2 inhibits proliferation and glycolysis of gastric cancer cells." (PMID 34872447, 2021). "HMGB2 facilitates carcinogenesis and is a novel biomarker for the diagnosis of gastric cancer." (PMID 34872447, 2021). "In addition, miR-23b-3p and miR-101 are able to reverse drug resistance of gastric cancer cells to multiple chemotherapeutics including VCR via targeting ATG12/HMGB2 as well as ANXA2." (PMID 32192494, 2020). "The MALAT1/miR-1297/HMGB2 regulator pathway provided a novel therapeutic method for gastric cancer." (PMID 28396617, 2017). "Therefore, the results demonstrated that MALAT1 negatively regulated miR-1297 and promote the HMGB2 expression in gastric cancer progression." (PMID 28396617, 2017). "Knockdown of HMGB2 decreased the chemoresistance of gastric cancer cells." (PMID 28396617, 2017). "Taken together, these results demonstrated that MALAT1/miR-1297/HMGB2 axis acted as critical regulator pathway in GC tumorigenesis and progression, which provided a novel therapeutic target for gastric cancer." (PMID 28396617, 2017).
gastric cancer (continued). "Thus, our results indicated that intervention of MALAT1/miR-1297/HMGB2 regulator pathway could inhibit gastric cancer progression." (PMID 28396617, 2017). "In conclusion, we demonstrated that MALAT1 was significantly overexpressed in gastric cancer tissues and cell lines and revealed a MALAT1/miR-1297/HMGB2 regulator pathway in GC." (PMID 28396617, 2017). "First, HMGB2 boosts the transcriptional activity of HIF-1α, leading to upregulation of glycolytic enzymes such as LDHA, PKM2, and HK2, which help gastric cancer cells sustain glycolysis under hypoxic conditions." (PMID 41220952, 2025). "miR-23b-3p regulates the chemoresistance of gastric cancer cells by targeting autophagy-related gene 12 (ATG12) and HMGB2." (PMID 35159393, 2022). "CENPU was an upstream protein of HMGB2, and CENPU enhances the expression level of HMGB2 in gastric cancer cells." (PMID 34872447, 2021). "Recently, existing research has specified that Malat1 regulates autophagy through the sponge of mir-23-3p, which targets HMGB2 and ATG12 in gastric cancer." (PMID 31425535, 2019). "In gastric cancer, for example, exogenous overexpression of miR-23b-3p has been found to reverse DDP resistance by modulating expression of autophagy related 12 (ATG12) and high mobility group box 2 (HMGB2)." (PMID 32192494, 2020). "In addition, over-expression of miR-23b-3p, an autophagy-related modulator, has been found to sensitize gastric cancer cells to 5-FU by inhibiting expression of ATG12 and HMGB2." (PMID 32192494, 2020).